ENSG00000273171 (novel protein, readthrough between VTN and SEBOX)
Gene: Protein-coding gene on chromosome 17 (28,364,288 to 28,368,012, reverse strand). Ensembl gene ENSG00000273171.
Genetic constraint (gnomAD): Loss-of-function variants: 14 observed, 18.74 expected, observed/expected ratio (o/e) 0.75, 90% interval 0.49 to 1.17. Missense variants: 205 observed, 212.37 expected, observed/expected ratio (o/e) 0.97, 90% interval 0.86 to 1.08. Synonymous variants: 77 observed, 72.64 expected, observed/expected ratio (o/e) 1.06, 90% interval 0.88 to 1.28.